EGFR (epidermal growth factor receptor)
Diseases named in the same sentence as EGFR in open-access papers (continued):
Sharing a sentence is not in itself a finding about the gene and the disease.
glioblastoma (continued). "Whereas EGFR is amplified in 50% of glioblastomas, half of these events is accompanied by an intragenic deletion, resulting in EGFR transcripts lacking exons 2–79,17." (PMID 29728634, 2018). "Glioblastoma represents an attractive therapeutic target for peptide vaccination as the unique epidermal growth factor receptor (EGFR) variant, EGFRvIII,is expressed in approximately 30% of patients with glioblastoma." (PMID 29854316, 2018). "We provide evidence of intratumoral subpopulations of cells with enhanced migratory behavior in human glioblastoma, selectively targeted via EGFR inhibition." (PMID 30573757, 2018). "MAbs with TK inhibitors targeting EGFR, a tyrosine kinase (TK), which is a receptor for therapeutic agents for glioblastoma such as T cells, oncolytic viruses, and nanoparticles is being investigated." (PMID 30374421, 2018). "Honokiol also Inhibits glioma/glioblastoma progression by targeting epidermal growth factor receptor." (PMID 30587839, 2018). "The RTKII group corresponds to the classic group of adult glioblastomas and is characterized by the high frequency of EGFR amplification, CDKN2A deletion, chromosome 7 gain, and chromosome 10 loss." (PMID 30279357, 2018). "Proliferation in many glioblastoma lines is highly dependent on EGFR signaling through AKT and ERK pathways." (PMID 29568378, 2018). "In agreement with that, PLK1 and EGFR inhibitor have been described as orthogonal therapeutic agents in glioblastoma, with enhanced tumoricidal activity when combined." (PMID 29844324, 2018). "A constitutively active mutant form of EGFR (EGFRvIII) has also been shown to upregulate TF expression in glioblastoma cells." (PMID 30093972, 2018). "RTK genes are frequently altered in glioblastomas; in fact, at least one RTK is altered in 65–75% of glioblastomas (EGFR (50–58%), PDGFRA (12–15%), MET (2–3%), and FGFR2/3 (3%))." (PMID 30279357, 2018). "Most recently, it was shown that EGFR overexpression or expression of EGFRvIII stimulates Rac1 activation and promote glioblastoma cell migration through activating the MLK3-JNK signaling axis." (PMID 30544910, 2018). "Of note, EGFR is known to be overexpressed in 50–70% of glioblastomas and has shown potential to provide robust tumor delineation from normal tissue due to its relatively low levels of expression in normal brain." (PMID 29623552, 2018). "Using single cell RNA sequencing data from glioblastoma, we enriched for genes co-expressed with EGFR, and further explored the GO bioprocesses and related pathways of EGFR." (PMID 30514230, 2018). "This agrees with the fact that EGFR activates mTORC2-NF-κB pathway in glioblastoma cells promoting growth, making these cells likely addicted to MTORC213." (PMID 29844324, 2018). "VSTM2A, LANCL2, SEC61G and VOPP1 were also amplified and are reported in the literature as fusion genes with EGFR in some glioblastoma patients." (PMID 29844869, 2018). "Chromothripsis occurred in 29.3% glioblastomas (36/123) and mostly affected chromosomes 7, 9 and 12, with amplification of oncogenes (EGFR, MDM2/CDK4), and homozygous deletion of tumor suppressor genes (CDKN2A)." (PMID 30542515, 2018). "The in vitro expression of ABCG2, at the transcription and at post-translational level, was significantly decreased in isogenic U87MG human glioblastoma cell lines by PD153035 (an EGFR antagonist)." (PMID 30181510, 2018). "For instance, WTAP is overexpressed in glioblastoma and regulates motility of glioblastoma cells by controlling the activity of EGFR." (PMID 30143009, 2018). "We propose the mechanism of action of sahaquine to implicate HDAC6 inhibition together with suppression of epidermal growth factor receptor and downstream kinase activity, which are prominent therapeutic targets in glioblastoma multiforme." (PMID 30302275, 2018). "For instance, overexpression or amplification of EGFR, mutations in IDH1 and IDH2 and phosphatase and tensin homologue (PTEN) mutations contribute to the pathogenesis of glioblastoma." (PMID 30382873, 2018).
glioblastoma (continued). "Here, the authors attach a photosensitive dye to tiny “affibody” ligands designed to seek out EGFR, which is often overexpressed in glioblastoma." (PMID 29313975, 2018). "Glioblastoma was modelled in Drosophila by expressing constitutively active forms of EGFR and PI3K, which is commonly observed in human glioblastomas." (PMID 29693007, 2018). "EGFRvIII-induced Fn14 expression, dependent upon STAT5 activation and requiring Src activation, is required for glioblastoma migration and survival; interestingly, Fn14 is also activated by normal EGFR, but through a signaling pathway involving MEK/ERK-STAT3." (PMID 30279357, 2018). "One of these molecular abnormalities is represented by the various genetic alterations (mutations, rearrangements, splicing alterations, and amplifications) of the EGFR occurring in ~57% of glioblastoma patients." (PMID 30279357, 2018). "They showed that the EGFR‐affibody combined with the photoreactive dye selectively kills glioblastoma cells overexpressing EGFR in mice." (PMID 29313975, 2018). "These EGFR-mutant glioblastomas are particularly sensitive to targeting with inhibitory EGFR antibodies." (PMID 30279357, 2018). "Complementary analyses were applied to a glioblastoma patient-derived xenograft model in order to quantitatively map distribution and resulting cellular response to the EGFR inhibitor erlotinib." (PMID 30464169, 2018). "This is of particular importance because EGFR is overexpressed or amplified in about 60% of primary glioblastoma and characteristic for a highly aggressive phenotype." (PMID 29389898, 2018). "The analysis of EGFR expression on cancer stem cell lines isolated from glioblastoma specimens showed that those expressing EGFR display a more malignant functional and molecular phenotype." (PMID 30279357, 2018). "It was later reported that EGFRvIII, a constitutively active EGFR mutant, stimulates the phosphorylation of Dock180 via Src, which stimulates Rac1 signaling, glioblastoma cell survival, and migration." (PMID 30544910, 2018). "Analysis of TCGA glioblastoma data demonstrates that at least 4% (16/434) of tumors harbor explicit co-amplification of EGFR and PDGFRA, however a much larger fraction of tumors show co-expression of the corresponding mRNAs at comparable levels." (PMID 28831081, 2017). "EGFR as a tumor-associated antigen overexpressed on the cell surface of various malignant tumors, such as NSCLC, glioblastoma, pancreatic cancer, HNSCC, renal cancer, and colorectal cancer (CRC)." (PMID 28931402, 2017). "EGFR is a cell surface protein that functions as an oncogene in many cancers due to aberrant activation and can promote invasion and migration in glioblastoma." (PMID 28800767, 2017). "The use of the EGFR tyrosine kinase inhibitors erlotinib and gefitinib have been evaluated in numerous clinical trials, alone and in combination with standard glioblastoma treatment, with minimal effect on patient survival." (PMID 29189740, 2017). "With our focus on glioblastoma, we show high intra- und interindividual variation of the ZEB1 labeling index and an association with EGFR amplification and IDH mutation, i.e. molecular traits of the classical and proneural subtypes, respectively." (PMID 28945795, 2017). "GBP1 expression is controlled by EGFR in glioblastoma and esophageal squamous head and neck cancers and is important for proliferation and tumor invasion." (PMID 29115931, 2017).
glioblastoma (continued). "Recently, a dual approach was tested: CK2 and epidermal growth factor receptor (EGFR), both of which are overexpressed in glioblastoma, were targeted by morpholino oligomeres attached to nanobioconjugates, in a mouse model of intracranial human glioblastoma." (PMID 28067771, 2017). "Knockdown of TRIM11 inhibits proliferation and migration of glioblastoma cells; it's also necessary for the activation of EGFR and MAPK pathways." (PMID 29254187, 2017). "We reproduced these results in two other EGFR-amplified cell lines, the human glioblastoma U87-MG and the epidermoid squamous A431 cells." (PMID 29084952, 2017). "First, we expressed the full-length or ectodomain of EGFR in LN229 glioblastoma cells and then immunized mice with LN229/EGFR or ectodomain of EGFR, and performed the first screening using enzyme-linked immunosorbent assays." (PMID 28891752, 2017). "Taken together, this establishes a SATB1 knockdown effect on two central factors in glioblastoma, EGFR and β-catenin." (PMID 28049521, 2017). "miR-128 is an antiproliferative miRNA that interferes with multiple pathways targeting genes involved in glioblastoma pathogenesis like EGFR and PDGFRA and WEE1 and E2F3a." (PMID 29234674, 2017). "Epidermal growth factor (EGF) and EGF receptor (EGFR) play prominent roles in the metastasis of glioblastoma (GBM)." (PMID 29029486, 2017). "This was ascribed to the relatively low percentage of newly diagnosed glioblastomas which express this EGFR mutant." (PMID 29244745, 2017). "For instance, expression levels of the epidermal growth factor receptor (EGFR) can be highly heterogeneous within glioblastoma multiforme, a particularly aggressive type of brain tumour." (PMID 28800767, 2017). "EGFRBi-armed CIK cells showed significant antitumor effects in EGFR-positive glioblastoma in vitro and in vivo." (PMID 28931402, 2017). "The glioblastoma samples were categorized into two subgroups based on the DNA copy number and mRNA expression level of EGFR." (PMID 28830458, 2017). "Recent study has demonstrated that EGFR amplified/overexpressing glioblastomas strongly benefited from metronomic temozolomide-based therapies." (PMID 28785587, 2017). "The targeting efficiency of the synthesized EGFR-SPIO nanoparticles was confirmed through Prussian blue staining and TEM images by using glioblastoma cell lines with high or low EGFR expression levels." (PMID 29166921, 2017). "EGFR, which was highly correlated to tumor response in our study has been found overexpressed in about 40% of glioblastomas with approximately 50% of tumors with EGFR amplification carrying a specific EGFR mutant (EGFRvIII)." (PMID 28754127, 2017). "GSCs have not only increased expression of ADAMs compared to NSCs but also elevated receptor tyrosine kinases whose ligands are shed by ADAM10 and ADAM17, in particular EGFR, which is often upregulated in glioblastoma." (PMID 27541285, 2017). "Antigen targets of interest have included interleukin-13 receptor alpha 2 (IL13Rα2) and EGFR on the basis that they are upregulated in more than 50% of glioblastoma multiforme." (PMID 28718815, 2017). "EMab-51 also reacted with LN229/EGFR more strongly than with endogenous EGFR-expressing LN229 glioblastoma cells." (PMID 29090976, 2017). "This has been investigated with NK-92 cells-expressing second-generation CARs targeting ErbB2, EGFR, or mutant EGFRvIII, which are expressed by a large proportion of human glioblastomas." (PMID 28572802, 2017). "In glioblastoma cell line T98G, EGFR upregulates the collagenase MMP-1 via mitogen-activated protein kinase (MAPK) signaling which leads to a decreased cell invasion." (PMID 28629170, 2017). "One mechanism for de novo resistance in glioblastoma to EGFR inhibitors is the ability of these cancers to reversibly up-regulate or suppress mutant EGFR expression, resulting in distinct cellular phenotypes to reach an optimal equilibrium for growth." (PMID 29371993, 2017).
glioblastoma (continued). "WTAP was found to promote the migration and invasion of glioblastoma cells by stimulating the epidermal growth factor receptor (EGFR)." (PMID 28212562, 2017). "Further, miR-331-3p was shown to regulate EGFR in glioblastoma cells resulting in reduced AKT activity." (PMID 29136645, 2017). "In conclusions, we found that the COX-2/sEH dual inhibitor PTUPB suppresses human glioblastoma growth in vitro and in vivo, and dramatically inhibits EGFR signaling pathway and expression of HMMR and stemness markers and regulators." (PMID 29152086, 2017). "Epidermal growth factor receptor (EGFR) gene amplification is present in ~ 50% of glioblastomas (GBMs)." (PMID 29075855, 2017). "Glioblastoma overexpressed wild type EGFR, EGFRvIII, and HER2, so they were all considered as attractive immunotherapy targets." (PMID 28931402, 2017). "This region contained the EGFR oncogene, known to be amplified in glioblastoma, with around 42% of cases showing amplification of this gene via double minutes." (PMID 28655341, 2017). "We show that PFKP is overexpressed in human glioblastoma specimens due to an increased stability, which is induced by AKT activation resulting from phosphatase and tensin homologue (PTEN) loss and EGFR-dependent PI3K activation." (PMID 29038421, 2017). "Downregulation of NHE9 expression by miR-135a acidifies sorting endosomes limiting EGFR trafficking to the glioblastoma cell membrane." (PMID 29268774, 2017). "Epidermal growth factor receptor mutations and phosphoinositide 3‐kinase (PI3K) hyperactivation are common in glioblastoma." (PMID 28097086, 2017). "In 2012, a unique conjugation based on anti-EGFR Nbs was introduced for malignant glioblastoma multiforme (GBM)." (PMID 29163515, 2017). "Dysregulation of epidermal growth factor receptor (EGFR/ERBB) family members due to their overexpression and/or mutation have been known to contribute to the etiology and progression of ovarian cancer and glioblastoma." (PMID 29321816, 2017). "The expression of amplified and aberrant EGFR combined with the expression of wildtype PTEN were important predictors for the sensitivity towards EGFR kinase inhibition in glioblastoma xenografts." (PMID 28611289, 2017). "This includes in-frame deletion of exons 2–7 (EGFRvIII), which is present in 50 to 60% of glioblastomas with EGFR amplification." (PMID 28785587, 2017). "EGFR is commonly upregulated in glioblastomas, and high expression of EGFR leads to Akt-activation through the phosphatidylinositol 3-kinase pathway and increased pSTAT3 expression." (PMID 28030813, 2017). "DCBLD2 is also upregulated in several cancers and can drive glioblastomas downstream of activated Epidermal Growth Factor Receptor." (PMID 29025973, 2017). "Many studies have reported genomic alterations of EGFR in glioblastomas affecting both the extracellular and intracellular domains." (PMID 29312333, 2017). "These cells have been modified to target neuroblastoma using a GD2 (disialoganglioside)-specific CAR and to target glioblastoma using either an ErbB2 (origin in the ERB-B gene responsible for avian erythroblastosis virus)-CAR or an EGFR-CAR." (PMID 28488245, 2017). "As glioblastomas often both overexpress EGFR and express EGFRvIII, this binding specificity has led to D2C7 being utilized as the basis of an immunotoxin currently being investigated for the treatment of these cancers." (PMID 27153091, 2016).
glioblastoma (continued). "This immunotoxin inhibited the viability of U87MG glioblastoma cells ectopically overexpressing EGFRvIII, as well as a panel of head and neck cancers with EGFR overexpression." (PMID 27153091, 2016). "IDH wild-type OT formed cluster C2 and had a genomic profile as typically observed in glioblastomas, characterized by gains of chromosome 7, EGFR amplifications, CDKN2A deletions and losses of chromosome 10." (PMID 27090007, 2016). "Taken together, our findings demonstrate that TAZ promotes glioblastoma growth through the EGFR/AKT/ERK pathway, and provide the evidence for promising target for the treatment of glioblastoma." (PMID 27167112, 2016). "Previously used as a therapeutic target in glioblastoma, here EGFR was used as a gateway to mediate intracellular delivery of Dox, restricting systemic exposure of normal tissues to the drug." (PMID 27050167, 2016). "Erlotinib, another selective EGFR inhibitor, also showed minimal effect to treat the recurrent glioblastoma (NCT00086879)." (PMID 26967052, 2016). "Perhaps the best example illustrating that GISTIC2 tends to call amplifications too focally is EGFR in glioblastoma." (PMID 27396759, 2016). "Growth advantage of glioblastoma through EGFR overexpression and/or activation is a common characteristic of GBM, representing 60% of cases." (PMID 27711187, 2016). "EGFR is often overexpressed in glioblastoma and anti-EGFR therapies are a potential targeted therapy in this difficult-to-treat disease." (PMID 25502460, 2016). "This molecule has undergone additional preclinical investigation for treatment of brain cancers with amplification or overexpression of EGFR, showing cell killing abilities at pM concentrations against a panel of human glioblastoma cell lines." (PMID 27153091, 2016). "Overexpression of EGFR (ErbB1) correlates with enhanced malignant potential of many human tumor types including glioblastoma." (PMID 27091344, 2016). "Given that PI4KIIα has roles in regulating both EGFR and AKT signalling, an initial aim of this study was to ascertain if the PI4K2A gene is mutated in glioblastoma." (PMID 25502460, 2016). "HER-2 is a member of the EGFR (epidermal growth factor receptor) family, overexpressed in breast and ovarian cancers, gastric carcinomas, glioblastomas, etc.." (PMID 26927159, 2016). "EGFR amplification was observed in 24 of 78 (30.8 %) glioma tumors and in 18 of 47 (38.3 %) glioblastoma tumors." (PMID 26839018, 2016). "For example, a combination of epidermal growth factor receptor (EGFR) pathway activation and loss of INK4A tumor-suppressor function induces a high-grade glioblastoma multiforme phenotype from differentiated astrocytes." (PMID 27768723, 2016). "In glioblastoma with epidermal growth factor receptor amplification, silencing FOXP1 expression inhibited epidermal growth factor receptor-dependent tumorigenicity." (PMID 26654944, 2016). "Our data provide first evidence that increased serum EGFR and ErbB2 levels can be detected in glioblastoma patients more than a decade before diagnosis, indicating that both proteins are important early in gliomagenesis." (PMID 26906551, 2016). "In confirmation of this dual-targeting, scFv(14E1)-ETA proved to be effective at killing glioblastoma cells displaying resistance to both cetuximab and EGFR TKI." (PMID 27153091, 2016). "On the other hand, as we have shown, too much emphasis on focality results in calling passengers (only) in close proximity to drivers (EGFR in glioblastoma being a good example)." (PMID 27396759, 2016). "Glorioso and Grandi chose EGFR as the target receptor expressed in a number of cancers, including glioblastoma." (PMID 26927159, 2016). "About 50% of glioblastomas are positive for EGFR amplification, half of which express accompanying EGFR mutation, encoding truncated and constitutively active receptor termed EGFRvIII." (PMID 27004406, 2016).